VASH1 (vasohibin 1)
Diseases named in the same sentence as VASH1 in open-access papers (continued):
Sharing a sentence is not in itself a finding about the gene and the disease.
tumor (continued). "However, since in vitro tests cannot mimic the tumor microenvironment in vivo, VASH1 only acts on tumor cells, inhibiting the decline in stability of tumor cells after its expression, thereby promoting the proliferation ability of tumors." (PMID 36504559, 2022). "Some of PMDGs were confirmed as tumor-suppressive genes, such as VASH1, ALX3, and LDN3." (PMID 32701143, 2020). "Considerable research suggested that knockdown of VASH1 might be a crucial driver of tumor lymphangiogenesis." (PMID 30254211, 2019). "Nevertheless, this negative feedback system may be defective in tumor angiogenesis, as factors in the tumor microenvironment such as hypoxia and inflammation inhibit VASH1 expression in endothelial cells." (PMID 30254211, 2019). "These previous results strongly suggest that the status of VASH1 density could serve as an index of the malignant potential of tumor angiogenesis, and also the level of VASH1 expression might influence unfavorable pathologic findings." (PMID 29535800, 2018). "VASH1 expression is restricted to the endothelial cells of blood vessels in the tumor stroma." (PMID 29135410, 2018). "Importantly, using the loss-of-function and gain-of-function strategies, we found that VASH1 expression in tumor cells was critical for cell growth, adhesion and migration in vitro, and controlled tumorigenesis and metastasis in vivo in animal models." (PMID 25797264, 2015). "Notably, our studies also demonstrated that VASH1 expression levels in normal paracancerous tissues were also negatively correlated with higher tumor sizes." (PMID 25797264, 2015). "Since senescent human cells have permanent growth arrest, we therefore determined whether senescence induction mechanism was also involved in the suppressed cell growth and proliferation mediated by overexpression of VASH1 in tumor cells." (PMID 25797264, 2015). "Furthermore, the numbers and sizes of tumor cell colonies were also significantly increased in HCT116 cells after knockdown of VASH1 gene in a colony formation assay." (PMID 25797264, 2015). "Furthermore, knockdown of VASH1 in HCT116 tumor cells significantly promoted the migration of tumor cells compared with the control shRNA-transfected tumor cells in a transwell migration assay." (PMID 25797264, 2015). "We next investigated whether knockdown of VASH1 gene promoted tumor metastasis using our previously established adoptive transfer tumor models." (PMID 25797264, 2015). "Besides the tumor growth, we also verified the effects of VASH1 overexpression on tumor cell proliferation, apoptosis, senescence, and angiogenesis in tumor tissues." (PMID 25797264, 2015). "In addition, knockdown of VASH1 expression in HCT116 cells significantly increased Ki-67+ cell populations in the tumor tissues." (PMID 25797264, 2015). "In addition, tumor sizes collected from the VASH1 shRNA group on day 33 post inoculation were significantly larger than those in the control shRNA group." (PMID 25797264, 2015). "However, little information is known about the role of VASH1 in the regulation of tumor angiogenesis, oncogenesis, and clinical outcomes of human colorectal cancer." (PMID 25797264, 2015). "Furthermore, VASH1 has also been found in cancer pathological conditions as a critical angiogenesis regulator involved in the tumor angiogenesis inhibition and prevention of tumor growth and metastasis in animal tumor models." (PMID 25797264, 2015). "In support of our prediction, a more recent study has suggested that enhancer of zeste homologue 2 (EZH2), a member of the polycomb group of genes (PcG), is overexpressed in human cancer tissues and can directly induce VASH1 methylation and promote tumor angiogenesis." (PMID 25797264, 2015). "Notably, the average tumor weights obtained from the VASH1 shRNA group also showed much higher than that of control shRNA group." (PMID 25797264, 2015).
tumor (continued). "We reasoned that VASH1-mediated inhibition of HT29 tumor cells may also be due to the same mechanism as in endothelial cells." (PMID 25797264, 2015). "We observed the increase of tumor lymphangiogenesis and regional LN metastasis in VASH1 (−/−) mice." (PMID 24066086, 2013). "However, the extent of coverage by mural cells was significantly less in tumor vessels of the VASH1 (−/−) mice." (PMID 24066086, 2013). "Indeed, we confirmed the significant increase of lung metastatic nodules in VASH1 (−/−) mice with the same weight of tumor-bearing legs." (PMID 24066086, 2013). "We previously reported that tumor growth and tumor angiogenesis were augmented in VASH1 (−/−) mice." (PMID 24066086, 2013). "Importantly, our present results further explored that endogenous VASH1 possesses the inhibitory effect on tumor angiogenesis and LN metastasis." (PMID 24066086, 2013). "However, the weight of tumor-bearing leg was less than 2 fold, whereas the number of metastatic nodule was more than 3 fold in VASH1 (−/−) mice." (PMID 24066086, 2013). "Nevertheless, since tumor vessels in WT mice were considerably immature, there might be an additional reason for the enhanced metastasis in VASH1 (−/−) mice." (PMID 24066086, 2013). "Additional tumor models have to be studied to identify tumor types that are sensitive to an antiangiogenic therapy consisting of gene therapy or systemically administered VASH1 protein or peptides." (PMID 19682397, 2009). "Moreover, VASH1 controls the tumor microenvironment by regulating immunocyte infiltration." (PMID 38010374, 2023). "Notably, miR-221-3p has been reported to act as a tumor promoter in multiple types of cancers, involved in tumor invasion, metastasis, proliferation and chemotherapy resistance by regulating the expression of target genes such as VASH1, PARP1, RB1." (PMID 36991449, 2023). "In addition, we also found that VASH1 expression has a certain correlation with the immune cell response signaling pathway, and through immunohistochemical staining, we found that VASH1 is not only expressed in tumor cells and endothelial cells, but also in small quantities in lymphocytes." (PMID 36504559, 2022). "Furthermore, multivariate analysis showed that tumor recurrence (HR = 2.375 and P=0.028), WHO grade (HR = 2.679 and P=0.031), IDH1 wild-type (HR = 6.473 and P < 0.001), and high VASH1 expression (HR = 4.996 and P < 0.002) were independent risk factors for LGG patients." (PMID 36504559, 2022). "As a new vascular regulator derived from endothelial cells, VASH1 can fight against pro-angiogenesis factors and has a negative feedback effect on angiogenesis, and has been found to be related to the occurrence and development of a variety of tumors, becoming a popular “player” in tumor research." (PMID 36504559, 2022). "The aim of this study was to determine the strength of a correlation of VASH1 expression as tumor microenvironment between the area of intratumoral and normal tissue, and to assess whether VASH1 expression could reflect the grade of malignancy throughout the prostate." (PMID 29535800, 2018). "The possibility may exist that VASH1 expressing in tumor cells is nonfunctional because of the mutation or methylation." (PMID 25797264, 2015). "In addition to the tumor growth and colony formation, we next investigated whether VASH1 expression in tumor cells is critical for the capacity of cell adhesion and migration." (PMID 25797264, 2015). "Thus, we considered that the immature tumor blood vessels in VASH1 (−/−) mice might be one reason for the augmentation of cancer metastasis." (PMID 24066086, 2013). "Thus, the spatiotemporal expression pattern of VASH1 is maintained even in tumor angiogenesis." (PMID 27713261, 2010). "In addition, we found that VASH1 inhibits tumor lymphangiogenesis and tumor LN metastasis." (PMID 27713261, 2010). "Therefore, the efficiency of the antiangiogenic effect of VASH1 might strongly depend on the tumor type analyzed." (PMID 19682397, 2009).
tumor (continued). "Second, the distinct roles of VASH1 and VASH2 in the tumor microenvironment suggest avenues for investigating their interactions with other angiogenic factors, such as VEGF, and immune checkpoint pathways to optimize targeted therapies and immunotherapies." (PMID 40483461, 2025). "VASH1 and VASH2, as regulators of angiogenesis, exert opposing effects, while NO influences vascular dynamics, collectively shaping the tumor microenvironment." (PMID 40483461, 2025). "Assessing angiogenesis-regulating markers, including VASH1, VASH2, and iNOS, in circulating WBCs provides deeper insights into the tumor microenvironment and immune response in HNSCC, surpassing the limitations of plasma measurements alone." (PMID 40483461, 2025). "These markers, including vasohibin-1 (VASH-1), CD31, and endoglin, can predict tumor progression and prognosis." (PMID 40565098, 2025). "Our study found that VASH1 and NO signaling in WBCs decreased after HNSCC tumor resection, highlighting their potential for monitoring therapeutic responses." (PMID 40483461, 2025). "This likely stems from the removal of the tumor-driven angiogenic microenvironment, where tumors secrete factors like VEGF that stimulate VASH1 and iNOS expression in WBCs, enhancing NO production to support vascularization." (PMID 40483461, 2025). "We compared the immunohistochemical expression of CD34, VASH1, and carbonic anhydrase 9 (CA9) between patients who achieved tumor clearance at operation (ypT0) and those with residual disease after cystectomy." (PMID 38376711, 2024). "To this end, we evaluated the expression and relationship between MVD and VASH1 in transurethral resection (TUR) specimens acquired before NAC, focusing on angiogenic activity in the tumor microenvironment." (PMID 38376711, 2024). "In the ypT0 cohort, high MVD, high VASH1 density, and strong CA9 staining were observed more frequently in patients who achieved tumor clearance at the time of the operation." (PMID 38376711, 2024). "Untreated tumors showed VASH1 mainly close to vascular structures in the extracellular matrix, whereas VASH2 was found within tumor cells." (PMID 35145607, 2022). "Further study on the molecular mechanism of VASH1 affecting the genesis and development of LGG will help to identify molecular targets for tumor therapy and provide clues for the development of new and more powerful antitumor tools." (PMID 36504559, 2022). "Previous studies found that the expression of VASH1 was restricted to ECs of blood vessels in the tumor stroma, and correlated with the expression of VEGF and FGF-2 in tumor cells." (PMID 29535800, 2018). "The knockdown efficiency on VASH1 expression by the shRNA was further confirmed in both VASH1-transfected 293T cells and in HCT116 tumor cells, using western-blot and Real-time PCR analyses, respectively." (PMID 25797264, 2015). "In contrast to VASH-1, VASH-2 has been shown to promote tumor growth." (PMID 40497943, 2025). "Our study carefully contrasted the expression of VASH1 in pancancer and nontumorous tissues in a public database to explore its regulatory role in clinical prognosis, diagnosis, tumor purity, and immune cell infiltration." (PMID 38010374, 2023). "Distinct from VASH1, VASH2 was also found in the tumor cells." (PMID 35145607, 2022). "It considers the target of the tumor cells, pointing to a therapeutic strategy not based on VASH1 and 2 molecular structures, but on their different expression sites." (PMID 35145607, 2022). "EZH2 in CAFs can participates the peritoneal tumor formation of GC by demethylating H3K27me3 markers; On the other hand, CAFs-derived VEGF promoting the proliferation and angiogenesis of human umbilical vein endothelial cells via regulating EZH2/VASH1 pathway." (PMID 36401232, 2022).
tumor (continued). "Although higher levels of VASH1 are associated with poorer prognosis for some cancers, this may be due to increased VASH1 feedback in vivo and inhibition of angiogenesis factors (VEGF, FGF-2, and VASH2) in the tumor microenvironment." (PMID 36504559, 2022). "The results showed that both VASH1 and IDH1 were independent predictors of prognosis in LGG patients, and high VASH1 expression was significantly correlated with IDH1 wild-type status, while further reflecting tumor progression and recurrence status." (PMID 36504559, 2022). "In addition, m6A modification can also regulate the expression of VEGFA through the miR-143-3P/VASH1 axis, as well as through the regulation of SERPINE2, IL11, and HDGF stability, thus affecting tumor angiogenesis." (PMID 33926508, 2021). "Firstly, the cell cycle delay observed upon VASH1/2 and VASH2 deletion might unveil the importance of VASH2 for proper cancer cell proliferation and tumor development." (PMID 33114575, 2020). "Moreover, we examined the relationship of VASH1 density and MVD according to the prostatic location focusing on tumor heterogeneity." (PMID 29535800, 2018). "In their studies, they provided mixed information and did not separate the analyses of clinical relevance with VASH1 expression in tumor cells or in endothelial cells." (PMID 25797264, 2015). "As was reported previously, vasohibin-1 can act in a negative feedback loop to help suppress neovascularization within an experimental tumor transplant model, a retinal neovascularization model, and a corneal micropocket model." (PMID 20680097, 2010). "Thus, VASH1 released from endothelial cells or cells of the immune system could inhibit fibroblast proliferation in the tumor stroma and inhibit pro-angiogenic tissue remodeling in the reactive stroma of the tumor and support differentiation processes of mural cells." (PMID 19682397, 2009). "For instance, CAFs secreted vascular endothelial growth factor (VEGF) in the surrounding tumor sites to promote the proliferation and angiogenesis of human umbilical vein endothelial cells (HUVECs) via enhancer of zeste homolog-2 (EZH2) /vasohibin 1 (VASH1) pathway." (PMID 35971182, 2022). "In addition, adenoviral transfer of human VASH1 gene to mice inoculated with Lewis lung carcinoma cells not only inhibited tumor angiogenesis but also matured remaining tumor vessels." (PMID 28835895, 2017). "K19 may enhance tumour angiogenesis by regulating FGFR1, VASH1, and VASH2 in HCC." (PMID 27863477, 2016). "Furthermore, we confirmed, using the H & E staining on sections from embedded liver and lung tissues, that high amount of tumor cells infiltrated into livers and lungs obtained from VASH1 shRNA treatment group, but not from the control shRNA treatment group." (PMID 25797264, 2015). "However, prior studies have not explored whether tumor resection specifically affects VASH1 or VASH2 concentrations in cancer patients." (PMID 40483461, 2025). "Our study revealed significantly higher VASH1 levels in HNSCC patients compared to non-cancer controls, with no notable difference in VASH2 levels, reflecting their distinct roles in the tumor microenvironment." (PMID 40483461, 2025). "Additionally, we investigated the influence of the tumor process on these markers by comparing their baseline levels in plasma (VASH1, VASH2, NO) and circulating WBCs (VASH1, VASH2, iNOS) between HNSCC patients and non-cancer controls." (PMID 40483461, 2025). "In addition, VASH1 expression resulted in a high OS and RFS in the diagnosis of tumor and nontumor tissues and negatively regulated tumor purity." (PMID 38010374, 2023). "The VASH1 was detected in the extracellular matrix (ECM) and EC but not in tumor cells." (PMID 35145607, 2022). "Although VASH1 and VASH2 have opposite effects on tumor angiogenesis, they may not always exert opposite functions in various pathological processes." (PMID 32604722, 2020).
cancer (29 papers, 2010 to 2025). A tumor composed of atypical neoplastic, often pleomorphic cells that invade other tissues. "VASH1 is a candidate prognostic and diagnostic marker for many types of cancers and can be used to evaluate the infiltration of immune cells into malignant tissues." (PMID 38010374, 2023). "There was a significant increase in the transmigration of cancer cells across the monolayer of VASH1-deficient HUVECs." (PMID 24066086, 2013). "Given the same tendency that VASH1 expression is associated with poor prognosis of cancer, VASH1 may be upregulated in kidney diseases in order to counter cellular stress such as local inflammation." (PMID 28835895, 2017). "Patients with HNSCC (n = 15) exhibited elevated baseline levels of VASH1, NO, and leukocyte-induced iNOS phosphorylation compared to non-cancer controls (n = 15)." (PMID 40483461, 2025). "Plasma VASH1 concentration was significantly higher in cancer patients compared to non-cancer controls (2425 ± 1493 pg·mL−1 vs. 1402 ± 368 pg·mL−1, p = 0.0097 by Mann–Whitney U tests; Kolmogorov–Smirnov test, p < 0.0100)." (PMID 40483461, 2025). "According to the ROC curve results, VASH1 is also of high value in the prediction and diagnosis of general cancer, with high sensitivity and a low false-positive rate." (PMID 38010374, 2023). "We explored the differential expression of VASH1 in distinct carcinomas by using multiple databases." (PMID 38010374, 2023). "Taken together, the results demonstrate that VASH1 was correlated with sensitivity to diverse drugs from the Cancer Therapeutic Response Portal database." (PMID 36504559, 2022). "VASH1 overexpression promotes cancer cell apoptosis and senescence and inhibits tumor occurrence and metastasis." (PMID 35252180, 2022). "Accordingly, pharmacological inhibition of calpains was shown to increase vasohibin-1 levels in the cancer cells, which led to a reduction in migration of adjacent ECs." (PMID 32266045, 2020). "Such VASH1-induced vessel maturation led to enhanced anticancer effect of cisplatin, probably due to the improved delivery of the agent to cancer cells." (PMID 28835895, 2017). "We found that cancer stroma VASH1 was positively correlated with its expression in paracancerous normal tissues." (PMID 25797264, 2015). "Recent studies suggest that VASH1 is a novel angiogenic molecule that is critical for cancer angiogenesis and prognosis." (PMID 25797264, 2015). "We found the prevalent expression of VASH1 in endothelial cells in both cancer stroma and paracancerous normal tissues." (PMID 25797264, 2015). "The correlations between cancer stroma VASH1 expression level and expressions of CD34, D2-40, VEGF-A, VEGF-C in cancer tissues were analyzed." (PMID 25797264, 2015). "Similar to our findings, several previous reports had demonstrated that an elevated expression of VASH1 predicted a worse clinical outcome in patients with cancer." (PMID 25255225, 2014). "Similar to the present findings, previous reports had demonstrated that an elevated expression of VASH-1 predicted a worse clinical outcome in patients with cancer." (PMID 24915146, 2014). "Histological analyses have shown that the expression of VASH1 is evident in ECs during angiogenesis under both physiological and pathological conditions including cancers." (PMID 24066086, 2013). "Here we examined the role of endogenous VASH1 in cancer metastasis in relation to the interaction between cancer cells and the vasculature." (PMID 24066086, 2013). "In summary, we concluded endogenous VASH1 to be required for the resistance of the endothelium against the intravasation of cancer cells needed for metastasis." (PMID 24066086, 2013). "To evaluate the possible role of VASH1 in cancer metastasis, we inoculated LLC cells subcutaneously in the right hind footpad of WT and VASH1 (−/−) mice." (PMID 24066086, 2013).